SPDYC (speedy/RINGO cell cycle regulator family member C)
Description:
Promotes progression through the cell cycle via binding and activation of CDK1 and CDK2. Involved in the spindle-assembly checkpoint. Required for recruitment of MAD2L1, BUBR1 and BUB1 to kinetochores. Required for the correct localization of the active form of Aurora B in prometaphase.
Synonyms: Ringo2; RINGOC
Tractability: No criterion of Open Targets' tractability assessment is met for any kind of drug.
Gene: Protein-coding gene on chromosome 11 (65,170,233 to 65,173,374, forward strand). Ensembl gene ENSG00000204710.
Subcellular location: Cytoplasm
Gene Ontology:
Molecular function: protein binding; protein kinase binding
Cellular component: nucleus; cytoplasm
Genetic constraint (gnomAD): Loss-of-function variants: 25 observed, 32.69 expected, observed/expected ratio (o/e) 0.76, 90% interval 0.56 to 1.07. The upper end of that interval is the gene's LOEUF score, 1.07, which puts it in group 4 of 6, group 1 being the genes least tolerant of losing a copy. Missense variants: 349 observed, 386.73 expected, observed/expected ratio (o/e) 0.9, 90% interval 0.83 to 0.99. Synonymous variants: 133 observed, 141.86 expected, observed/expected ratio (o/e) 0.94, 90% interval 0.81 to 1.08.
Homologues: Orthologues: macaque SPDYC (98% identical), chimpanzee SPDYC (96% identical), pig SPDYC (68% identical), dog SPDYC (62% identical). Paralogues in human: SPDYA (36% identical).
Diseases named in the same sentence as SPDYC in open-access papers:
SPDYC is named in the same sentence as 4 diseases in open-access papers, as found by Europe PMC text mining. Sharing a sentence is not in itself a finding about the gene and the disease. The quoted sentences say what the papers report.
breast carcinoma (4 papers, 2021 to 2024). "SPDYC has been identified to be negatively correlated with the outcome of breast cancer and belongs to the speedy/Ringo cyclin-dependent kinase (CDK) family with functions in cell cycle transitions and progression." (PMID 37212877, 2023). "Furthermore, MTRNR2L12 pseudo‐gene, HBB, and SPDYC were already reported as possible prognostic markers in breast cancer, where their overexpression in tumor cells led to unfavorable prognosis." (PMID 38887841, 2024).
cancer (1 paper, 2024). A tumor composed of atypical neoplastic, often pleomorphic cells that invade other tissues. "A deeper examination of the feature importance of the cancer detection model has revealed the top five transcripts at play: FKBP5, TMSB4XP8, MTRNR2L12, HBB, and SPDYC." (PMID 38887841, 2024). "The exploration of the feature importance of the cancer detection model has pinpointed the top five transcripts characterized by their largest weight on prediction outcomes: FKBP5, TMSB4XP8, MTRNR2L12, HBB, and SPDYC." (PMID 38887841, 2024).
SPDYC also shares sentences with these, for which no sentence is quoted: bacterial infection (1 paper); tumor (1).